TLR4 (toll like receptor 4)
Diseases named in the same sentence as TLR4 in open-access papers (continued):
Sharing a sentence is not in itself a finding about the gene and the disease.
Sepsis (continued). "We found a significantly higher percentage of intracellular TLR4-positive NK cells in SIRS and sepsis patients for both CD56bright and CD56dim cells in comparison to healthy controls." (PMID 23098236, 2012). "For the first time, we explored TLR2, TLR4 and TLR9 expression on and in human blood NK cells during sepsis." (PMID 23098236, 2012). "Nevertheless, in comparison to healthy controls and sepsis patients, SIRS patients showed an increase in the percentage of surface TLR4-positive cells for both NK subsets." (PMID 23098236, 2012). "The constructed decoy receptor was shown to attenuate the TLR4-mediated signaling process by trapping MD2, implicating a potential therapeutics for bacteria-induced sepsis and inflammation." (PMID 22363519, 2012). "In kidney tissue after sepsis, TLR2 and TLR4 mRNA is highly expressed in the WT mice, which also have a six-fold increased expression of MyD88." (PMID 22655058, 2012). "When taken together these data suggest that in response to sepsis, SRA interacts and/or cooperates with TLR4 to enhance NFκB activation and cytokine/chemokine expression with a concomitant increase in inflammatory phenotype and mortality." (PMID 23071440, 2012). "Among them, TLR2, TLR4, and TLR9 have been established to play a key role in the mediation of systemic responses to invading pathogens during sepsis." (PMID 21219635, 2011). "While further development in sepsis patient is unlikely, the potential benefit of TAK 242 in other TLR4 related diseases, such as autoimmune diseases, has to be assessed." (PMID 20396414, 2010). "The results presented herein demonstrating an association between TLR-4 expression and exacerbated inflammation in mice fed western diet suggest that targeting the TLR signaling pathway as a therapeutic approach to the medical management of sepsis may be especially beneficial in obese patients." (PMID 20958969, 2010). "Thus, a lack in TLR4 signaling may be associated with a worse outcome of disease, which also correlates with the recent findings suggesting that immunosuppression caused by negative regulators of TLR signaling are associated with sepsis mortality." (PMID 20525286, 2010). "In summary, our studies describe a novel association between common genetic polymorphisms in sequential elements of the endotoxin recognition system (TLR4 and the intracellular signaling adaptor TIRAP/Mal) and the course of sepsis and pneumonia." (PMID 20525286, 2010). "The monocyte expression of TLR2, TLR4 and CD14 was at all timepoints [admission (t0), day 1 (t1) day 3 (t2) and day 7 (t3)] significantly higher in patients with sepsis compared to the monocyte expression in healthy controls." (PMID 19371402, 2009). "By fusion of the Fc domain of IgG1 to TV3 and TV8, we were able to generate dimeric TLR4 decoy receptor TOY, which is effective in treating LPS- and bacteria-induced sepsis." (PMID 19816595, 2009). "In human sepsis increased protein expression and mRNA of TLR2 and TLR4 on blood neutrophils and monocytes are found compared to healthy individuals." (PMID 19371402, 2009). "The data presented here are consistent with a functional impairment of TLR4 and TLR9 agonist-induced cellular responses in MDCs and PDCs in patients with sepsis." (PMID 19604380, 2009). "Sepsis model rats administered LPS showed substantially greater TLR4-mRNA transcription than non-treated controls." (PMID 41585603, 2026). "Because many PRRs can be activated during sepsis, blocking only TLR4 is not sufficient to reduce cytokine induction." (PMID 39853914, 2025). "A significant number of sepsis cases result from Gram-negative bacterial-derived endotoxin, which evokes intensive inflammatory responses through the toll-like receptor-4 (TLR4) signaling pathway." (PMID 40725048, 2025).
Sepsis (continued). "As a ligand, RETN engages receptors such as TLR4 and CAP1 and activates the NF-κB signaling pathway, which promotes release of large amounts of proinflammatory cytokines and drives the systemic inflammatory response in early sepsis." (PMID 41472734, 2025). "Additionally, studies have revealed that Xuebijing exerts cardioprotective effects by inhibiting TLR4/IKKα-mediated NF-κB and JAK2/STAT3 signaling pathways, thereby attenuating inflammatory responses and apoptosis during sepsis." (PMID 40520010, 2025). "Inhibiting TLR4 activation reduces JNK protein expression in cardiomyocytes and serum TNF-α levels, alleviating myocardial injury and improving cardiac function during sepsis." (PMID 40640887, 2025). "In parallel to TLR4, the NLRP3 inflammasome—a pattern recognition receptor involved in innate immune responses—also plays a central role in inflammation and tissue injury in sepsis-induced AKI." (PMID 40869248, 2025). "Inhibition of pathogen-dependent TLR4 signaling via RANK-RANKL interactions may lead to reduced cytokine release and inflammation, thereby preventing organ dysfunction in sepsis." (PMID 41229429, 2025). "Our aim was therefore to expose the ex vivo perfused heart to a sepsis‐like state using sonicated E. coli fragments or LPS, with or without TLR4 inhibition." (PMID 39853914, 2025). "During sepsis, exosomes contribute to the progression of inflammation by carrying proinflammatory cytokines (such as IL-1β, IL-6, TNF-α) and activating Toll-like receptors (TLR2, TLR4, TLR7) in immune cells." (PMID 41268545, 2025). "In an in vitro cellular system of human lung epithelial cells, sEVs isolated from neutrophils of patients with sepsis induced inhibition of cell proliferation and activation of pyroptosis through the NOD-like receptor family pyrin domain containing 3/Toll-like receptor 4 (NLRP3/TLR4) pathway." (PMID 41010852, 2025). "This regulatory effect is further modulated by the interaction of miR-374a-3p with toll-like receptor 4 (TLR4), suggesting a complex network in which miRNAs, lncRNAs, and immune receptors coordinate the inflammatory response during sepsis-induced kidney injury." (PMID 41153411, 2025). "Ultimately, multiple signaling axes, including TLR4, IL-18, NADPH oxidase isoform 4 (NOX4), and the Janus kinase/signal transducer and activator of transcription-1/3 (JAK/STAT1/3) pathway, contribute to sepsis-induced acute kidney injury." (PMID 41415561, 2025). "Furthermore, the FDA-approved antidiarrheal drug nifuroxazide improves cardiac structure by suppressing the TLR4/NLRP3 pathway in LPS-induced cardiac inflammation 172, although NLRP3's role in sepsis-induced myocardial injury remains in early investigation." (PMID 40520010, 2025). "In LPS-induced sepsis rat model, PF pretreatment inhibited PI3K/Akt/ERK-mediated HIF-1α and TLR4/MyD88/NF-κB signaling, thereby reducing inflammation by decreasing the levels of tumor necrosis factor-α (TNF-α) and interleukin-1β (IL-1β) in serum and cardiac tissue." (PMID 41311552, 2025). "The pharmacological blockade of TLR2 and TLR4 signaling by antagonistic antibodies or small molecule inhibitors (e.g., TAK-242 for TLR4) successfully reduced the disease severity in bacteria-induced sepsis mouse models 13-15." (PMID 40963927, 2025). "In the early stage of sepsis, exogenous PAMPs, such as LPS derived from gram-negative bacteria, are recognized by TLR4 on the host cell membrane, and intracellular infection or stress signals activate TLR7 and TLR8 in intracellular host vesicles." (PMID 38352879, 2024). "Given the role of TLR4-TIR acetylation by CBP and HDAC1 in LPS-induced NF-κB activation, we conducted further investigations into the impact of CBP inhibitor and HDAC1 inhibitor on the polarization of M1 macrophages and the progression of sepsis." (PMID 39294473, 2024). "In murine models of sepsis, TLR2 and TLR4 are upregulated in hepatic and splenic macrophages." (PMID 38835761, 2024).
Sepsis (continued). "Moreover, investigating TLR4 and other regulatory pathways will provide insights into how CD44-ICD interacts with broader molecular networks during sepsis." (PMID 39201593, 2024). "Besides TLR4, several genes, including IFIH1 and STAT1, can affect M1 macrophage polarization and contribute to the progression of sepsis." (PMID 39294473, 2024). "Investigation of TLR4 inhibition has been shown to be clinically feasible as small molecule inhibitor of TLR4, TAK-242, has been used in a clinical trial for use in the treatment of sepsis and has proven to be safe for use in humans." (PMID 38585277, 2024). "Previous studies have shown that (+)-borneol inhibits the activation of the NF-κB signaling pathway in mice with sepsis and in microglia and ischemic stroke models, but the effect of (+)-borneol on its upstream TLR4 has not been investigated." (PMID 39605791, 2024). "In the context of sepsis and sepsis-induced renal injury, necroptosis is predominantly initiated downstream of death domain receptors (such as tumor necrosis factor receptor(TNFR) and Fas) and Toll-like receptors (TLR4 or TLR3)." (PMID 39544947, 2024). "In summary, NCTP could alleviate sepsis-induced acute lung injury by regulation of the NLRP3 and TLR-4/NF-κB pathways and the gut microbiota." (PMID 38673868, 2024). "Given that thanatin blocks the LPS-stimulated TLR4 signaling pathway, resulting in the inhibition of proinflammatory cytokine induction, we investigated the levels of such cytokines upon Tha-PA90 treatment in mice with A. baumannii sepsis." (PMID 38622637, 2024). "In addition, in CLP-induced sepsis mice, the expression levels of AST, ALT, and sCr in the peripheral blood were lower in KO mice compared to WT mice, whereas the overexpression of TLR4 resulted in corresponding increases in these organ injury markers." (PMID 39455728, 2024). "Contrary to the expression patterns observed for anti-apoptotic markers, we found that pro-apoptotic and pro-inflammatory markers Caspase-3, P2X7R, TLR4, IL-1Β, and TNF-α saw a considerable surge in the CLP group, a reflection of the pronounced inflammatory response instigated by sepsis." (PMID 38546748, 2024). "Moreover, DHEA administration in mice following sepsis induction resulted in the restoration of TLR expression, particularly TLR2 and TLR4 mRNA, in splenic macrophages." (PMID 38792602, 2024). "Animal experiments further support the involvement of TLRs in sepsis and pneumococcal lung infection: mice with experimental sepsis exhibit a cytokine pattern dependent on NF-κB and MAPKs and TLR2 and TLR4 knockout (KO) mice display less effective cytokine release compared with wild mice." (PMID 38835761, 2024). "In addition, the suppression of inflammation, cell apoptosis and pyroptosis by blocking Toll-like receptor 4 (TLR4) signaling and NLRP3 inflammasome pathways has been shown to alleviate myocardial dysfunction in sepsis." (PMID 38378646, 2024). "Furthermore, knockout of TLR4 results in decreased mortality and expression of IL-6 and TNF-α, with better global ventricular function in a sepsis animal model." (PMID 37600769, 2023). "This pathway induces sepsis when activated by cytosolic LPS without the requirement of TLR4, termed the noncanonical inflammasome." (PMID 37700349, 2023). "Up to now, no study has reported the regulatory effect of MAF on the TLR4/myD88/NF‐κB signaling pathway during sepsis, let alone its effect on the intestinal flora." (PMID 38455195, 2023). "Particular attention has been paid to TLR4, the receptor for the Gram-negative bacteria outer membrane lipopolysaccharide (LPS) or endotoxin, and the therapeutic targeting of TLR4 in sepsis, because of its essential role, looks promising." (PMID 37605037, 2023).
Sepsis (continued). "In this research, using Paquinimod (Paq, also known as ABR25757), an S100A8/A9 specific inhibitor which prevents S100A8/A9 to bind to TLR4, we explored the role of S100A9 in the development of septic AKI in a murine model of cecal ligation and puncture (CLP)-induced sepsis." (PMID 37547329, 2023). "We show further that the direct contact between CD4 molecule of CD4+ T cells or the ectodomain of CD4 (soluble CD4, sCD4), and MHC II of resident macrophages is necessary and sufficient to prevent TLR4 overactivation in LPS and cecal ligation puncture (CLP) sepsis." (PMID 37332010, 2023). "Over-activation of Toll-like receptor 4 (TLR4) is the key molecular pathology of Gram-negative bacterial infection-induced sepsis, in which regulation of mitochondria remains elusive." (PMID 37175593, 2023). "Overall, targeting TLR4 signaling, particularly TLR4-TRAM-TRIF–dependent signaling, could be beneficial for the treatment of sepsis patients." (PMID 37788908, 2023). "The absence of TLR4, a classic upstream target of phosphorylated NF-κB signaling pathway, ameliorates sepsis-induced organ damage by downregulating activated inflammatory and apoptosis-associated proteins." (PMID 37650558, 2023). "Moreover, platelets were activated by TLR4 and its downstream mediator IKK controlled platelet secretion during sepsis." (PMID 37928258, 2023). "During physical exercise, muscle and adipose tissue produce a substance called irisin, which decreases the expression levels of TLR3, TLR4, MyD88, MAPK, and NF-kB, thereby reducing the release of pro-inflammatory factors and preventing the development of sepsis." (PMID 38049851, 2023). "During sepsis, LPS within the cell wall of Gram-negative bacteria can transduce extracellular signals by activating intrinsic immune recognition by TLR-4." (PMID 38161332, 2023). "The aims of this study were to investigate whether TLR4/IKKα-mediated NF-κB and JAK2/STAT3 pathways were involved in XBJ's cardio-protection during sepsis and the mechanisms." (PMID 37650558, 2023). "Interaction of LPS with Toll-Like Receptor 4 (TLR4) on immune cells, such as macrophages, leads to strong pro-inflammatory activation of these cells, which can lead to severe tissue damage and, in extreme cases, sepsis." (PMID 37895956, 2023). "Besides this, the CRIP release in sepsis is also reported to trigger adaptive immune system in the spleen by activating T-lymphocytes such as CD4+ and CD8+ T cells in a TLR4-depentent manner." (PMID 36865547, 2023). "miR-22 can inhibit the inflammatory response, target the HMGB1, and inhibit the HMGB1/TLR4/NF-kB pathway, to attenuate the sepsis-induced AKI, which indicates that miR-22 may serve as a potential treatment target in sepsis-induced AKI." (PMID 35960478, 2023). "During sepsis, activated BMVECs express various adhesion molecules, including CD40, e-selectin, VCAM, ICAM, and inflammatory receptors, such as IL-1, TNF-α and TLR4, which facilitate the infiltration of leukocytes and inflammatory mediators into the brain parenchyma." (PMID 36817492, 2023). "Over-activation of Toll-like receptor 4 (TLR4) is the key mechanism in Gram-negative bacterial infection-induced sepsis." (PMID 37175593, 2023). "In our study, phosphorylation of NF-κB and levels of TLR4 and MyD88 proteins in the model group increased after LPS stimulation, but these factors were significantly inhibited by EA at ST36 in the alleviation of sepsis." (PMID 35722155, 2022). "The results indicated that 8 genes (MAPK14, MAPK8, TLR4, MAP3K5, CYBB, DUSP1, MAPK1 and ATM) might be closely related to the occurrence of sepsis." (PMID 36117534, 2022). "LPS, a major constituent of gram-negative bacterial cells, is a ligand of TLR4 that induces inflammatory syndromes, such as multiple organ injury and sepsis, and is generally recognized as a key factor in inducing ALI." (PMID 35386914, 2022).
Sepsis (continued). "More recent evidence suggests that sepsis affects neither platelet TLR4 expression nor classical platelet activation, although platelets did respond to LPS by an increase in mitochondrial respiration." (PMID 35741086, 2022). "As oxidative stress contributes to the activation and amplification of the inflammatory potential in DCs, they suggested that activation of TLR4 upregulates BTK signalling in DCs, which is likely an essential contributor to the development of sepsis-induced AKI." (PMID 36010680, 2022). "Administration of MD2-TLR4 antagonist Eritoran has shown effective downregulation of TLR4 in animal model of sepsis, but did not proof to be effective in patients." (PMID 35237675, 2022). "TLR4-mediated chronic inflammation plays key roles in pathogenesis of numerous inflammatory diseases and malignancies, and of systemic inflammatory response syndrome (SIRS) in sepsis." (PMID 35712350, 2022). "In our study, whole lung levels of nuclear factor kappa B (NFkb1) and toll-like receptor 4 (Tlr4) were not significantly altered by Rabeprazole treatment in basal or sepsis-challenged mice." (PMID 35563731, 2022). "For instance, toll-like receptor 4 (TLR4) was initially characterized in mice as the pattern recognition receptor (PRR) for LPS, and represents a significant milestone in improving our understanding of the immunopathology of sepsis." (PMID 35990662, 2022). "Pyroptosis plays critical roles in LPS‐induced sepsis, including via canonical and noncanonical pathways, toll‐like receptor 4 (TLR4)‐dependent and TLR4‐independent pathways, Gasdermin D (GSDMD) and beyond‐GSDMD‐mediated pathways." (PMID 35593197, 2022). "LPS, a major component of the outer membrane of Gram-negative bacilli, can generate an in vitro sepsis model and promote platelet activation by Toll-like receptor 4 (TLR4)." (PMID 35563812, 2022). "Only wt-EVs were capable to mount sepsis-like reactions and TLR2 and TLR4 activation." (PMID 35203650, 2022). "Therefore, the selective blocking of BTK may provide greater benefits to patients than blocking the whole TLR4 pathway, and BTK may be an ideal target for intervention in patients under the condition of systemic inflammatory response and organ dysfunction caused by burn sepsis." (PMID 35280898, 2022). "In the present study, we investigated that Paneth cells were significantly ablated in the crypt in the sepsis group, with exhibited significantly fewer LYZ and HD-5, which was inversely correlated with TLR4 expression levels in small intestinal epithelial cells." (PMID 36088483, 2022). "The lncRNA MALAT1 can alleviate sepsis in burn-injured patients by regulating miR-214/TLR5; the lncRNA CRNDE is involved in aggravating the inflammatory process of sepsis through the miR-181a-5p/TLR4 axis." (PMID 36274974, 2022). "Meng’s group also showed that endotoxin lipopolysaccharides via TLR4 signaling pathway to activate translocation of NF-κB and further regulate expression of pro-inflammatory genes, including TNF-α, IL-6, and IL-1β during sepsis." (PMID 35370629, 2022). "Considering that TLR4, but not other TLR pathways, is commonly activated in sepsis, we performed an in‐depth analysis of the expression of TLR4 signal pathway protein." (PMID 35474613, 2022). "Blocking the TLR4 pathway with TAK242 can improve heart dysfunction and myocardial damage in sepsis, while blocking the Notch pathway with DAPT cannot effectively prevent heart dysfunction and myocardial damage in sepsis." (PMID 35891967, 2022). "However, the most promising small-molecule inhibitor of TLR4, TAK242, failed in a Phase III study in a clinical trial in patients with sepsis or respiratory failure." (PMID 35281916, 2022). "Clinical success of Toll-Like receptor-4 (TLR-4) antagonists in sepsis therapy has thus far been lacking." (PMID 36230982, 2022). "However, MD2/TLR4 inhibitors Eritoran and TAK242, unfortunately, both failed in phase 3 clinical trials as anti-sepsis agents." (PMID 35803916, 2022).